EGFR (epidermal growth factor receptor)
Diseases named in the same sentence as EGFR in open-access papers (continued):
Sharing a sentence is not in itself a finding about the gene and the disease.
tumor (continued). "Five studies investigated the relationship between tumor size and EGFR mutation status: a total of 299 NSCLCs with average size ranging from 1.92 to 2.7 cm with inherited EGFR mutation and 433 tumors measuring between 1.43 and 3.74 cm without EGFR mutation were pooled into the meta-analysis." (PMID 28068946, 2017). "Because numerous studies have shown increased cisplatin sensitivity after inhibition of EGFR, HER2/neu or VEGFR in different tumor entities, we performed combination assays despite the relative resistance of our investigated cell lines towards AEE788." (PMID 28591197, 2017). "Previous studies have suggested that IGF1R signaling is involved in both acquired EGFR TKI resistance in NSCLC and induction of EMT in some types of tumor." (PMID 29190911, 2017). "OCP on cfDNA confirmed high level EGFR amplification in UMUC-5, and high level AR amplifications in VCaP and 23 of 23 (100%) high tumor content mCRPC samples." (PMID 29163793, 2017). "In conclusion, our preclinical data in HNSCC provide both a unique view of EGFR, HER2, and ErbB3 signaling and a mechanistic rationale to combine EGFR and ErbB3-targeting therapies for the treatment of this tumor type." (PMID 28723928, 2017). "Significant decreases in tumour size were clearly observed among the mice that received pWPXL-miR-135a, LCL-miR-135a, and Anti-EGFR-CIL-miR-135a compared with blank control mice." (PMID 28729631, 2017). "In our study there was tumor overexpression of EGFR (2 times more) and KRAS (5 times more) compared to tumor-free lungs." (PMID 29285236, 2017). "Finally, the intratumoral heterogeneity of EGFR mutation status has been described in several studies (ranges from 13.9% to 27%;) demonstrating that tumor biopsy do not systematically reveal the complete genomic landscape of the whole patient tumoral cell population." (PMID 28146051, 2017). "Levels of total and phosphorylated EGFR, c-Met and ERK1/2 protein in tumor lysates were measured as indicators of receptor down-modulation (total EGFR and c-MET protein) and signaling pathway inhibition (phosphorylated protein)." (PMID 27786612, 2017). "Biologically, the result of decreased tumor sensitivity to cetuximab is plausible since an inverse relationship has been demonstrated between HPV status and EGFR expression." (PMID 29050332, 2017). "In blocking study, the tumor uptake of 64Cu-PCTA-cetuximab was markedly reduced in SNU-1066 xenograft models, which represent the specificity of EGFR targeting of 64Cu-PCTA-cetuximab." (PMID 29190900, 2017). "Over time, fluorescence intensity in the tumours of mice treated with Anti-EGFR-CIL-Cy5.5 was significantly higher than that of mice treated with LCL-miR-Cy5.5, and fluorescence gradually concentrated at tumour sites in the 24-hour group." (PMID 28729631, 2017). "Epidermal growth factor receptor (EGFR) and insulin-like growth factor 1 receptor (IGF-1R) both overexpressed on non-small cell lung cancer (NSCLC) and are known cooperatively to promote tumor progression and drug resistance." (PMID 28460483, 2017). "Most known oncogenes (e.g. EGFR, FGFR1, MYC, ERBB2) or tumor suppressors (e.g. CDKN2A, NOTCH1) were detected to reside within the focal SCNA regions." (PMID 29348864, 2017). "Besides TGF-β receptors, epidermal growth factor receptor and integrin α3β1 core fucosylation has been shown to potentiate their ligand binding ability and thus may enhance downstream signal pathways to support tumor growth and metastasis." (PMID 28982386, 2017). "Overexpression of EGFR, HER2/neu and VEGFR has been found in many tumor entities, e.g. colon, lung and ovarian cancer, head and neck tumors as well as breast cancer." (PMID 28591197, 2017). "We selected four - cyclin D1 and p 21 that interfere in cell cycle and are related with cell proliferation, EGFR and VEGF related with angiogenesis and tumor progression." (PMID 28938543, 2017).
tumor (continued). "Consistent with the results of the tumor metastasis experiments, miR-338-3p inhibition or EYA2 knockdown markedly attenuated the ability of EGFR to regulate the EMT markers." (PMID 28703807, 2017). "In tumor tissues of NSCLC patients, the relative expression of miR-542-5p in patients with high EGFR protein expression was significantly lower than that of patients with low EGFR protein expression (0.739 ± 0.407 vs 3.049 ± 1.194, t = 7.753, p < 0.001)." (PMID 28927388, 2017). "After 9 days of cetuximab treatment the expression of EGFR, pEGFR and Ki67 was significantly decreased in UT-SCC-14 tumours as compared to untreated controls." (PMID 28756482, 2017). "Here, we explore the anti-tumor activity of KTN3379 (also known as CDX-3379) in HNSCC and evaluate dual ErbB3/EGFR blockade with KTN3379 and cetuximab." (PMID 28723928, 2017). "The expression levels of membrane EGFR, and nuclear FAK, Slug and ZEB1 were decreased in the xenograft tumours of CXB-treated mice." (PMID 28740192, 2017). "Due to the targeted effects of Anti-EGFR-CIL-miR-135a, the GBC tumour growth rate was 60% lower in an in vivo xenograft-bearing mouse model compared to controls." (PMID 28729631, 2017). "Sym004 exhibited significant tumor growth inhibition in a subset of ESCC cell lines in vitro and in vivo with pronounced activities in comparison with other anti-EGFR monoclonal antibodies, cetuximab and panitumumab." (PMID 28038457, 2017). "We propose the following mechanistic sequence of events: tumor stroma and/or tumor cells release PGE2, which couples with EP3 receptor and orchestrates a complex mechanism culminating in EGFR activation and translocation into the nucleus." (PMID 28415726, 2017). "The epidermal growth factor receptor (EGFR), is highly variable in tumor cells and an important regulator of cell growth and survival." (PMID 28427242, 2017). "Considerably, analysis of SM-related modules revealed multiple tumour-promoting pathways such as PI3K-Akt, PLD, and EGF/EGFR SPs which were commonly found in the NSCLC group." (PMID 29062084, 2017). "EGFR expression was analysed in our series based on previous reports of EGFR overexpression in TGCT cases and its value as a prognostic factor in other tumours." (PMID 28320414, 2017). "PD-L1 expression was detected in 21 (30.4%) and 11 (15.9%) of 69 post-EGFR-TKI specimens using cut-offs of 1–49% and ≥50% in tumor proportion score (TPS), respectively." (PMID 29296194, 2017). "GLS1 was also reported to be regulated by series of oncogene or tumor-suppressors including Rho GTPase, ERBB2, EGFR, most have bearing on transcriptive regulation." (PMID 27902968, 2017). "Over-expression of the epidermal growth factor receptor (EGFR, ERBB1) has for many years been recognized as a biomarker for tumor cell growth, invasion and resistance to chemotherapy [1, and references therein]." (PMID 29163826, 2017). "Soluble tumor biomarkers (notably CEA, EGFR, HER2, MUC1, PSA) were detected on aptamer-based analytical platforms with low limits of detection." (PMID 28635657, 2017). "Similarly, considering the PPV (91.2%, 31/34) and NPV (67.1%, 49/73) of EGFR detection with CastPCR in our study, for patients whose tumor tissue is not enough or unavailable, EGFR mutation detection with CastPCR in cfDNA could be first choice." (PMID 28572536, 2017).
tumor (continued). "In summary, our study shows that the combination of cetuximab with celecoxib enhances the anti-tumor efficacy of both drugs in CRC cells, and reduces CSC subpopulation, due to impairment of EGFR-RAS-FOXM1-β-catenin signaling axis." (PMID 28423516, 2017). "Due to their frequent overexpression in tumours, research efforts especially concentrated on EGFR (HER1) and HER2 [for review:]." (PMID 27933395, 2017). "The intensity of pY1068 signal was proportional to the intensity of GFP (EGFR-GFP) signal, suggesting the relatively homogenous activation of EGFR within the tumor." (PMID 29268862, 2017). "EGFR plays an essential role in IBC progression and is correlated with Syndecan-1 expression in some tumor entities." (PMID 28270211, 2017). "Overall, the present results provide novel insights into the potential of LA to activate the EGFR/ERK/AP1/p21Cip1/WAF1 transduction signaling toward antiproliferative and pro-apoptotic responses in tumor cells." (PMID 28924490, 2017). "In the xenograft tumor model study, we found that tumor volume and weight in mice inoculated with RPN2- or EGFR-silenced CRC cells were significantly decreased compared with control mice." (PMID 29069815, 2017). "Similarly, univariate analysis of OS data showed that female patients and those with an ECOG PS of 0, no smoking history, an EGFR-sensitive mutation, and a tumor response had a significantly longer median OS (P = 0.026, 0.000, 0.011, 0.000, and 0.000, respectively)." (PMID 29156802, 2017). "The epidermal growth factor receptor (EGFR) is an important regulator of cell growth and survival, and is highly variable in tumor cells." (PMID 28427242, 2017). "Sorafenib is the only drug approved for advanced HCC; however HCC tumor cells develop resistance to sorafenib treatment by modulating many signaling pathways, including PI3K/Akt and EGFR/Her-3." (PMID 27419635, 2017). "The inappropriate activation of upstream molecules, such as EGFR, Raf, and Ras, constitute major forces controlling the constitutive activation of the ERK pathway in tumor cells." (PMID 28431406, 2017). "The top 10 unpaired normal (n=4 samples) to tumor (n=11 samples) increased protein kinases were SYK, ZAP70, ARG (ABL2), ERBB3, ABL, TEC, MER (MERTK), AXL, EGFR and ERBB2." (PMID 28423512, 2017). "It has recently been demonstrated that EGFR amplification is an early event in GBM development, while EGFRvIII subsequently emerges during disease progression to drive a more aggressive tumor that becomes dependent on angiogenesis for growth." (PMID 28797294, 2017). "In line with this, knockdown of CD82 expression by sh/CD82 or miR-197 in Drosha-silenced MGC-803 cells resulted in the increased expression of p-EGFR, p-ERK1/2 and MMP7, which rendered the tumor cells with a marked invasive potential." (PMID 28252644, 2017). "In order to demonstrate the possibility of antitumor efficacy of cetuximab in the BRGS mouse model, we performed a similar tumor challenge using the cetuximab-sensitive A431 cell line, which bears wild-type RAS and overexpresses EGFR." (PMID 28220124, 2017). "Examining the very high expressing cases (with Tumor Cell Score ≥ 2.5, indicating high protein expression throughout the tumor), EGFR+ERBB2 expression was only observed in one GU tumor, while two UroA tumors expressed both EGFR and ERBB3 at high levels." (PMID 28388586, 2017). "Between December 2007 and April 2011, tumor samples from 149 subjects were screened for EGFR gene copy number by fluorescence in-situ hybridization (FISH), Out of 49 patients with positive EGFR FISH test, 45 were treated with erlotinib." (PMID 27924059, 2017). "Plasma protein levels of VEGF and EGF, gene mutations of KRAS, BRAF and PIK3CA, and expression of P27, phosphorylated EGFR and AKT in tumor tissues were also investigated for their potential roles as biomarkers of clinical outcomes." (PMID 28288572, 2017).
tumor (continued). "Several lines of evidence suggest that EGFR and its downstream signaling pathway regulate the epithelial-mesenchymal transition (EMT) and tumor invasion process." (PMID 29100426, 2017). "Immunohistochemical analysis of the tissue micro array derived from these patients established the functional correlation between the decreased expression of tumor suppressive miRNAs and their target oncogenes: ERBB2, EGFR, EPHA2, BAX, GNA12, GNA13, and JUN." (PMID 28740575, 2017). "In this study we characterize wide-ranging patterns of EGFR and PDGFRA co-expression among single cells sorted from patient-derived GBM tumor sphere (GTS) lines representing a selection of the most common genotypes, not restricted to co-amplified tumors." (PMID 28831081, 2017). "In in vivo studies accumulation of NP was observed in MDA-MB-468 xenografts and tumour uptake was enhanced by the coadministration of 15 μg of the unlabelled targeting ligand, EGF, to block hepatic EGFR." (PMID 29071190, 2017). "EGFR signalling is elevated in FLCN−/− tumours and the EGFR inhibitor afatinib suppresses the growth of human FLCN−/− cells as tumour xenografts." (PMID 28656962, 2017). "A number of other anti-tumor antibodies are directed against molecules expressed by a large variety of cell types (HER2/neu, EGFR, etc.)." (PMID 28855903, 2017). "EGFR/ERK signaling is an important pathway in the regulation of cellular proliferation, and plays an indispensable role in tumor initiation and development." (PMID 28039459, 2017). "Our recent publications demonstrate that the tumor microenvironment is a critical driver of the IBC clinical phenotype and EGFR signaling plays an important role in mediating the crosstalk between IBC tumors and their microenvironment." (PMID 28978083, 2017). "Currently, the only available data regarding resistance to the third-generation EGFR-TKI osimertinib were analyzed in AURA clinical study on tissue re-biopsies or circulating tumor DNA samples from resistant patients." (PMID 28416737, 2017). "Immunocytochemical staining after cetuximab treatment shows a significantly decreased expression of EGFR, pEGFR, Ki67, CAIX and nuclear HIF-1α in UT-SCC-14 tumours compared to untreated controls." (PMID 28756482, 2017). "Clusters and/or vesicles containing EGFR-GFP, as well as their movement, appearance and disappearance, were occasionally observed in cells located at the periphery of tumor nodules." (PMID 29268862, 2017). "Overexpression of NF-κB, EGFR can activate PAR-1 signaling, which consequently promotes tumor cell growth and invasion." (PMID 29291033, 2017). "These include EGFR IHC/FISH, FGFR FISH, MET IHC and PD-L1 IHC for respective targeted therapy agents in a variety of tumor histologies." (PMID 29246028, 2017). "Notably, ligand-activated EGFR can be targeted to the nucleus, where it acts as transcription factor and chromatin regulator and affects gene expression, DNA replication, and DNA damage repair promoting tumor progression, aggressiveness and resistance to therapies." (PMID 28415726, 2017). "LINC00152 knockdown also suppresses cell proliferation and tumor growth, and LINC00152 has been shown to directly bind with epidermal growth factor receptor (EGFR), thereby activating phosphoinositide 3-kinase (PI3K)/serine/threonine kinase (AKT) signaling." (PMID 28719640, 2017). "The development of minimally invasive assays to detect gene mutations may provide a promising alternative to tumour biopsy, in the absence of available tissue samples, for identifying patients who would benefit from genotype-directed therapy such as EGFR-targeted agents." (PMID 28006816, 2017). "Afatinib selectively inhibits ErbB1, ErbB2, ErbB4 and especially EGFR mutants (L858R and T790M) which inhibits tumor progression as well as angiogenesis." (PMID 28615068, 2017).
tumor (continued). "Experiments in vitro with the cancer cell line, which was derived from this xenograft tumor, showed that the blockade of AXL and SMO, of SMO and EGFR, and, more efficiently, of AXL and EGFR was able to revert the resistance to EGFR." (PMID 28416737, 2017). "We studied 80 primary and 12 metastatic ccRCC tumors and identified 7 peptide substrates with significantly increased tyrosine phosphorylation by metastatic samples relative to primary tumor samples including FGFR1, FAK1, ACHD, K2C8, EGFR, EPHB4 and MBP." (PMID 28418903, 2017). "We also observed that the levels of EGFR, K-Ras and p-ERK1/2 were markedly increased in mouse tumor injected with FOXD3-knockdown HCT116 cells compared with the controls." (PMID 27926503, 2017). "In BR28, for example, relatively high frequencies of EGFR p.R521K and PTCH1 p.T1195S over ATM p.H1380Y, BRCA2 p.N289H, and BRCA2 p.N991D were observed in plasma compared to tumor tissue data, indicating tumor heterogeneity." (PMID 29156805, 2017). "89Zr-cetuximab uptake was quantified using standardized uptake value (SUV) and tumor-to-background ratio (TBR), and correlated to EGFR immunohistochemistry." (PMID 27965472, 2017). "Their studies demonstrated that combinations of selective inhibitors targeting HER2 and EGFR were able to significantly inhibit the growth of cetuximab-resistant CRC cells, and induce long-lasting tumor regression in experimental models." (PMID 28002810, 2017). "HCaRG/COMMD5 acts as a tumor suppressor gene of RCC and as such restoring its levels to control EGFR/ErbB signaling holds potential to treat cancer." (PMID 29050225, 2017). "To explore the clinical relationship among EGFR activation, SCD1 Y55 phosphorylation and SCD1 protein expression, we carried out immunohistochemistry (IHC) analysis of the tumor tissue microarray comprising 90 NSCLC samples." (PMID 28724430, 2017). "We observed that the two PDECX models with EGFR gene amplification (PDECX1T0326 and PDECX1T0950) were most sensitive to theliatinib treatment demonstrating tumor regression of 32% and 75%, respectively, at the end of study." (PMID 28881608, 2017). "Co-targeting EGFR and PI3K resulted in enhanced tumor growth control in vivo than either inhibitor alone." (PMID 28532501, 2017). "Collectively, these results demonstrated that EGFR knockdown exhibited a similar phenotype as miR-34a upregulation in NSCLC cells, and that the tumor suppressive function of miR-34a is mediated partly by the downregulation of EGFR." (PMID 28825720, 2017). "To understand the dynamics of EGFR and DR5 on tumor cells post ENb-TRAIL binding and subsequent activation of DR5, we engineered fusion constructs EGFR-YFP, DR4-CFP and DR5-CFP and co-expressed EGFR-YFP and DR5-CFP or DR4-CFP in 293T cells." (PMID 28572590, 2017). "EGFR and the insulin-like growth factor-1 receptor (IGF-1R) play an essential role in cell proliferation and tumor progression." (PMID 28931402, 2017). "Results indicated that the tumor was wild type for RAS, BRAF, and EGFR with a high microsatellite instability (MSI-H) profile." (PMID 28903424, 2017). "Both the EGFR and IGF-1R contributed to tumor development and progression through their effects on cell proliferation, apoptosis and angiogenesis, and both were overexpressed in NSCLC cells." (PMID 28460483, 2017). "We generated a bispecific antibody targeting EGFR and c-Met (JNJ-61186372) demonstrating anti-tumor activity in wild-type and mutant EGFR settings with c-Met pathway activation." (PMID 27786612, 2017). "SK-ChA-1 and A431 cells were used because the former are derived from a tumor known to be refractory to PDT and because both overexpress EGFR, which was shown to be profoundly affected by PDT." (PMID 27803950, 2017).